TNF (tumor necrosis factor)
Diseases named in the same sentence as TNF in open-access papers (continued):
Sharing a sentence is not in itself a finding about the gene and the disease.
lung carcinoma (continued). "Subepithelial lung myofibroblasts (SELMs) isolated from tissue biopsies of patients undergoing surgery for lung cancer were stimulated with TNF-α (50 ng/mL), IL-1α (5 ng/mL), added alone or in combination, and TGF-β1 (5 ng/mL)." (PMID 37509671, 2023). "In an experiment of C3G plus 5-FU (a commonly used basic chemotherapy drug) in nude mice against lung cancer, the inflammatory cytokine, IL-1β, IL-6 and TNF-α, COX-2, NF-kpa and PCNA was decreased." (PMID 36771198, 2023). "Ropivacaine treatment was shown to have beneficial antimetastatic effects on NCI-H838 lung cancer cells, potentially by suppressing tumor necrosis factor-α-induced src-activation and intercellular adhesion molecule-1 phosphorylation." (PMID 38034873, 2023). "In summary, this study reveals how TNFα-mediated inflammation reprograms lung cancer metabolism by downregulating the expression of HMGCL." (PMID 36923932, 2023). "The tumor necrosis factor (TNF) is a multifunctional cytokine that plays a variety of roles in cancer, including lung cancer." (PMID 37764733, 2023). "Previous studies have also found that capsaicin supplementation in lung cancer bearing mice considerably prevented the increaseof TNF-α, IL-6, COX-2 and NF-κB." (PMID 36771198, 2023). "Real time viability assays revealed higher PM21-NK killing of both ovarian and lung cancer cells expressing NA-Fc, which correlated with increased release of TNF-α and IFN-γ cytokines from NK cells and was dependent on CD16-Fc interactions." (PMID 37146009, 2023). "In EGFR-mutated lung cancer cell models, EGFR mutation leads to downregulation of miR21 expression, which stabilizes TNF mRNA and activates the TNF, thereby activating NFkB signaling pathways." (PMID 37483492, 2023). "Compared to the SPHK2 inhibitor Opaganib, which only reduces the release of IL-6 from PBMC of lung cancer origin, inhibition of SPHK1 by PF543 can down-regulate both TNF-α and IL-6 release and more effectively inhibit lung cancer progression." (PMID 36823149, 2023). "With a demographic skew toward older individuals and those with a history of lung cancer, the heightened TNF-α secretion possibly hints at a backdrop of chronic inflammation, or even a predisposition toward malignant processes." (PMID 37900310, 2023). "In lung cancer, high expression of S1P increases the release of TNF-α and IL-6 from PBMC of lung cancer origin." (PMID 36823149, 2023). "During cancer surgery, propofol anesthesia had an inhibitory effect on the release of TNF-α in esophageal cancer patients and contradictory results in lung cancer patients compared to inhalation anesthesia." (PMID 36765695, 2023). "In an in vitro model, astrocytes were shown to secrete inflammatory cytokines (IL-6, tumor necrosis factor-α (TNF-α) and IL-1β) in the presence of lung cancer cells, resulting in increased proliferation of the tumor cells." (PMID 37749707, 2023). "HIIT also downregulates TNF-α and iNOS expression in lung cancer tissue but increases IL-12 expression and plasma IFN-γ levels." (PMID 37691942, 2023). "CircTMEM30A is highly expressed in COPD patients with lung cancer, the circTMEM30A/hsa-miR-130a-3p axis regulates TNF-α and promotes the malignant progression of COPD with primary lung cancer." (PMID 36793900, 2023). "TNF-α is increased in the serum of patients with lung cancers and animal models of lung adenocarcinomas." (PMID 36241629, 2022). "The expression of NF-kB is downregulated, while the expression of c-Jun N-terminal kinase is potentiated that instigates apoptosis in lung cancer cells induced by tumor necrosis factor." (PMID 36482329, 2022). "The tumor regression from a lung cancer mouse model using CD8 T cell epitope was dependent on TNF-α levels." (PMID 36140220, 2022). "It is clear that the TNFα–NF-κB pathway is one of important pathways to control the progression of variant SARS-CoV-2 and lung cancer." (PMID 35706933, 2022).
lung carcinoma (continued). "We also examined the effect of independent variables (subtype and stage of lung cancer etc.)on hepcidin, IL-6, and TNF-α concentrations in male lung cancer patients." (PMID 36612220, 2022). "In this manner, miR-21 in lung cancer treated with EGFR TKIs is inversely upregulated and thus stimulates the TNF/NF-κB pathway, which consequently causes EGFR TKI resistance in lung cancer." (PMID 36139582, 2022). "In sharp contrast, S1P significantly increased the levels of TNF-α and IL-6 from lung cancer-derived PBMCs." (PMID 36010601, 2022). "We began the analysis by examining the effect of independent variables (subtype and stage of lung cancer, etc.), on the levels of hepcidin, IL-6, and TNF-α." (PMID 36612220, 2022). "The objective of this study was to describe the characteristics of hepcidin, IL-6, and TNF-α levels in anaemia of lung cancer patients with operative tumours." (PMID 36612220, 2022). "The activated TLR2 : TLR6 can induce TNF-alpha secretion by myeloid cells and enhance lung cancer bone metastasis growth." (PMID 36440359, 2022). "On the other hand, as a tumor promoter, TNF-α attenuated Fas-induced A549 human lung carcinoma cell death." (PMID 36140220, 2022). "Exosomal miR-21 and miR-29a from lung cancer cells activate mouse TLR7- and human TLR8-mediated NF-κB activation in immune cells and the production of proinflammatory IL-6 and TNF-α to promote lung cancer and metastasis in mice." (PMID 35562884, 2022). "Overexpression of Snail1 in lung cancer cells shows increased production of inflammatory cytokines TNF-α, IL-1β, and IL-6 by regulating macrophage activation." (PMID 36159784, 2022). "Treatment with I3C can also suppress the progression of inflammation-related lung cancer in mice by reducing the expression of tumor necrosis factor-α (TNF-α) and interleukin-6 (IL-6)." (PMID 35734410, 2022). "Meanwhile, ectopic expression of P65 also rescued S phase blockage and expression of cell cycle-related genes including CDK2, Cyclin D1 and Cyclin E1, in addition to NF-κB target genes including IL-1β, IL-6 and TNFα in lung cancer cells overexpressing ZNF24." (PMID 36457047, 2022). "Adding 10,000 ng of TNF-α in human lung carcinoma cells significantly suppressed replications of VSV, encephalomyocarditis virus (EMCV), adenovirus, and HSV-2 from 10- to 100-fold." (PMID 35268699, 2022). "In our previous studies, we found that lung cancer epithelial cells were responsive to exogenous S1P, but the major source of TNF-α was related to the activation of TLR9." (PMID 36010601, 2022). "Inflammatory cytokines related to lung cancer include IL-1β, IL-4, IL-6, IL-11, IL-12, TNF-α, monocyte chemotactic protein (MCP)-1, and TGF-β." (PMID 35898583, 2022). "Of the 12 cytokines, six (IL-6, IL-8, IL-10, IL-12p70, IFN-γ, and TNF-α) displayed a higher level in plasma of lung cancer patients compared with cancer-free smokers (All p < 0.001)." (PMID 36498497, 2022). "We supplemented our findings with a statistical analysis of the diagnostic value of hepcidin, IL-6, TNF-a, CRP, and SAA1 in the examination and differentiation of anaemia in lung cancer patients." (PMID 36612220, 2022). "A study confirmed that quercetin significantly enhanced tumor necrosis factor (TNF)-related apoptosis-induced ligand-mediated lung cancer cell death through activation of autophagy." (PMID 36467088, 2022). "TNF-α is a major inflammatory cytokine, and has been reported to play decisive roles in the complex process of lung cancer onset, progression, and dissemination." (PMID 35372052, 2022). "As a tumor suppressor, TNF-α played an essential role in CD8 T cell-mediated lung cancer cell elimination in vivo." (PMID 36140220, 2022). "In lung cancer cell cultures, TNFα induced similar WT1 cytoplasmic translocation through PKA-dependent phosphorylation and determined the overexpression of protein matrix metalloproteinase-9, which is normally silenced by WT1." (PMID 35453662, 2022).
lung carcinoma (continued). "We found that although HIIT did not down-regulate the mRNA level of CD86, it significantly down-regulated the mRNA levels of IL-6, TNF-α, and iNOS in lung cancer tissues, which also functions as an anti-inflammatory role." (PMID 36186906, 2022). "Recent studies have shown that Sotetsuflavone can inhibit the epithelial-mesenchymal transition, invasion, and metastasis of lung cancer cells in A549 cells through the TNF-α/NF-κB pathway." (PMID 35910766, 2022). "The pharmacological blockade of ceramidase and sphingosine kinases (SPHKs), key enzymes for S1P synthesis, completely reduced the release of both TNF-α and IL-6 after S1P addition on lung cancer-derived PBMCs." (PMID 36010601, 2022). "Our studies examining the adaptive response to EGFR inhibition in lung cancer has focused on the role of TNF." (PMID 34853306, 2021). "According to in vivo and in vitro lung cancer model studies, TNF-α triggers similar processes as IL-6." (PMID 34336101, 2021). "To further examine the effect of a combined EGFR plus TNF inhibition in an immunocompetent model, we used a well-established transgenic mouse model of lung cancer that is driven by doxycycline-mediated induction of the EGFR L858R mutation." (PMID 34853306, 2021). "Results of our current comprehensive study of cytokines did reveal that the transfection of miR‐1 into three different human lung carcinoma cell lines harboring EGFR mutations significantly decreased the expression of CCL5, CXCL10, IL‐6, IL‐8, and TNF‐α." (PMID 33305905, 2021). "TNF causes COPD and lung cancer promotion by supporting myeloid-derived suppressor cell (MDSC) accumulation within the tumor with subsequent tumor cell proliferation and increased angiogenesis." (PMID 33917839, 2021). "The TNF-α expression was significantly upregulated in the BSA-MG-AGEs/A549 lung cancer cell line as compared to the control group, with an average increase of 7.49-fold." (PMID 33928164, 2021). "In this study, we first identified the genetic variants of TNF-α 308G/A (rs1800629) and TNF-α 1031T/C (rs1799964) and their association with cachexia in pancreatic and lung cancer Egyptian patients." (PMID 34900737, 2021). "Moreover, loss of miR-708 in diseased lung cancer may contribute to uncoupled TNFα/IL-1β signaling." (PMID 33776573, 2021). "Previous studies indicated that MALT1 was required for the EGFR- and TNF-α/NF-κB signaling-induced IL-6 production in lung cancer progression." (PMID 33802402, 2021). "Our study also showed the suppression of TNF-α in patients with lung cancer receiving omega-3 supplementation, which improved nutritional status." (PMID 34395492, 2021). "High amounts of TNFR2+ Tregs have been found in the TME of murine as well as human advanced lung cancers, suggesting that Tregs are activated through TNFα/TNFR2 signaling." (PMID 34445397, 2021). "While the 238 G>A polymorphism, found in the promoter region of TNFα, has a favorable prognostic association for NSCLC, the 308 G>A polymorphism constitutes an increased risk for lung cancer." (PMID 34445397, 2021). "Biochanin A, an O-methylated isoflavone, inhibited the release of pro-inflammatory cytokines TNF-α and IL-6 from A427 lung cancer cells using the cocultured method." (PMID 34950252, 2021). "The inflammatory factors closely related to lung cancer are IL-1β, IL-4, IL-6, IL-11, IL-12, TNF-α, MCP-1, and transforming growth factor (TGF)-β." (PMID 34079469, 2021). "A study showed that Quercetin reduced the production of nickel-induced cytokines, such as IL-1β, IL-6, TNF-α, and IL-10, in lung cancer cell lines." (PMID 33918290, 2021). "Next we examined the effect of combining TNF and EGFR inhibition in lung cancer cell lines with EGFR activating mutations." (PMID 34853306, 2021). "First, several clinical studies have reported on the decisive role of TNFα in lung cancer EMT, invasion, and metastasis." (PMID 34445397, 2021).
lung carcinoma (continued). "For example, anti-TNFα antibody treatment has been tested together with an intrapulmonary IFN-beta immuno-gene therapy (Ad.IFNβ) in an orthotopic mouse model of lung cancer." (PMID 34445397, 2021). "Prior studies have reported that serum cytokine levels correlated with survival in lung cancer patients; in particular, IL-6, IL-8 and TNF-α." (PMID 34830880, 2021). "Taken together, TNF seems to have a tumor-promoting role in the case of lung cancer metastasis and inflammation-related tumorigenesis." (PMID 33917839, 2021). "In the present study, we found that treatment with TNF-α or IL-1β increases Oct4 expression in lung cancer cells through NF-κB." (PMID 32487125, 2020). "We demonstrated that the levels of IL-2, TNF-α, and IL-10 in the plasma from lung cancer patients were significantly higher than those in the plasma from healthy donors." (PMID 32788875, 2020). "The increased serum concentration of several cytokines, including VEGF, IL-6, TGF-β, and TNF-α, have been proposed as lung cancer biomarkers." (PMID 33125430, 2020). "TNF-alpha is a pro-inflammatory cytokine, and its overexpression is related to sarcopenia and cachexia in lung cancer patients." (PMID 32872195, 2020). "One study concluded that through the upregulation of MMP-13, TNF-α promotes tumor growth in lung cancer cells." (PMID 33262947, 2020). "Among them, TNF had the greatest degree in the HCT-major hub genes-disease network, while IL-6, JUN, EGFR, and MYC were shown to associate with the survival of lung cancer patients." (PMID 32595734, 2020). "For example, activation of TLR2 or TLR4 signals on TAMs increases the lung cancer metastasis via TNF-α and IL-6 production." (PMID 32788720, 2020). "As MK2 was shown to be involved in NF-κB-dependent transcription, we performed experiments to investigate the role of MK2 in TNF-α stimulated IL-6 transcription in lung cancer cells." (PMID 32647362, 2020). "An experiment in human lung cancer cell lines, observed that TNFα induced the expression of CLDN-1, and knockdown of CLDN-1 blocked 75% of TNFα-induced gene expression." (PMID 31952355, 2020). "We therefore performed Gene Set Enrichment Analyses (GSEA) on gene signatures of Notch and TNF signaling, both of which are important in maintaining lung cancer stemness." (PMID 32549341, 2020). "In lung cancer, TNFα found to induce cell proliferation, apoptosis resistance, angiogenesis, invasion, and metastasis in various in vitro and in vivo lung tumor models." (PMID 32219066, 2020). "Previous research also confirms that RAs produce IL-6, tumor necrosis factor-α (TNF-α), and IL-1β, all of which promote lung cancer brain metastasis." (PMID 33262947, 2020). "TNF-α was expressed within TB granulomas, with greater immunoreactivity than control lung tissue at the excision margin of lung cancer." (PMID 32091388, 2020). "One study suggested that TNFα-induced cell migration is through cytoplasmic CLDN1 in lung carcinoma cells." (PMID 32754286, 2020). "After PM10 exposure for 24 h, mRNA expression of the pro-inflammatory cytokines including TNF-α (5.5-fold) and IL-1β (8.8-fold) were increased in A549 lung cancer cells." (PMID 33374928, 2020). "We found that C1 had an obvious effect on TNF-α-induced endothelial cell barrier damage and verified its anti-tumor effect on lung cancer in vitro and in vivo." (PMID 32015677, 2020). "Tumor necrosis factor (TNF) has been investigated to be correlated with the occurrence and progression of lung cancer." (PMID 32552897, 2020). "In the past few years, antidiuretic hormone (ADH), tumour necrosis factor alpha (TNF-α), NF-κB/p65, COX-2 and thyroid transcription factor-1 (TTF-1) have been reported to be associated with the prognosis of lung cancer." (PMID 32312252, 2020). "A study dating back to 2000 suggests that NF-κB activation increases lung cancer cells’ resistance to TNF-α." (PMID 33262947, 2020).
lung carcinoma (continued). "In osteoblasts, it has been shown that down‐regulation of STAT‐1 or STAT‐3 reduces the expression of CCL‐234 and in a lung cancer cell line, STAT‐1 was linked to IL‐8 expression, whereas TNF‐α synthesis is regulated via NFκB signalling." (PMID 32374474, 2020). "Next, we demonstrated the in vitro anti-lung cancer effects of C1 on endothelial cell migration by inhibiting TNF-α-induced HUVEC damage in the endothelial barrier." (PMID 32015677, 2020). "Tumor promoting inflammation is also a hallmark of cancer and our laboratory and many others have established a role for inflammatory pathways, such as TLR4, TNF, NFκB, among many others, in lung cancer development." (PMID 31018556, 2019). "To that end, we stimulated lung cancer cells, A549, with TNFα and IFNγ and analyzed the changes in both the cellular proteome and HLA presentation." (PMID 30833945, 2019). "Among them, TNF-α contributes to the survival and metastasis of lung cancer, while the level of TNF-α in the tumor tissues and serum obtained from patients with NSCLC has increased significantly along with the clinical stage of the tumor." (PMID 31766230, 2019). "The expression of these proteins was upregulated by TNF-α in various types of cancer cells including lung cancer." (PMID 31766230, 2019). "Using a model of reversible EMT based on a TNFα/TGFβ treatment of the lung cancer cell line A549, they showed an up-regulation of PD–L1, with a demethylation of its promoter via the NFκB pathway." (PMID 31546725, 2019). "In lung cancer cells, TNF-α-induced inflammation, survival, and metastasis via the MAPKs signaling pathway have been reported." (PMID 31766230, 2019). "Currently anti-TNF therapy is being used in different types of cancers, including lung cancer, and has been shown to enhance chemotherapeutic effect by decreasing inflammation, proliferation, and metastasis." (PMID 32039025, 2019). "Because TNF-α plays an important role in lung cancer metastasis, the effects of dicentrine on TNF-α-induced A549 cells invasion and migration were investigated." (PMID 31766230, 2019). "In our murine lung cancer model, we found a significantly reduced secretion of soluble TNFα by M1 macrophages and impaired secretion of soluble TNFα by CD4+ and CD8+ T cells." (PMID 30647851, 2018). "In lung cancer models, tarin decreased metastasis by leading to an increase in the levels of TNF-alpha, IL-6, and IL-12 cytokines." (PMID 30403726, 2018). "In contrast, TNF-α secretion by the unstimulated PBMCs was significantly lower in the lung cancer patients relative to controls." (PMID 30365491, 2018). "Previous studies have shown IL-1, IL-6, and TNF-α increase in lung cancer patients and these cytokines progressively decrease as the clinical stage of cancer progresses." (PMID 30365491, 2018). "In contrast, TNF-α secretion by unstimulated PBMCs was lower in lung cancer than controls, while maintaining inducibility status via the TLR4/LPS pathway." (PMID 30365491, 2018). "By literature mining, we found that these genes of TNF-α signaling via NF-kB pathway are involved in human diseases such as lung cancer, respiratory, and cardiovascular dysfunctions." (PMID 29703138, 2018). "The present study shed light on its lung cancer chemoprevention properties by studying its inhibitory activity on TNF-α-induced NF-κB activity, its proapoptotic and antimigration activity on A549 cells, as well as its ability to inhibit the Wnt pathway." (PMID 29534536, 2018). "In the human lung cancer cells, from which the CM was derived for the ex vivo culture, TNF, IL6 and IFNB1 were upregulated upon Snail OE, while IFNG was undetectable." (PMID 30190790, 2018). "The ability of IL-6 to inhibit tumor cell growth has been suggested, as IL-6 functions synchronously with IL-1 and TNF-α in order to support anti-tumor immunity and has been shown to regulate the ability of AMs in lung cancer to be stimulated by IFN-γ and LPS." (PMID 30365491, 2018).